CDKN2A (cyclin dependent kinase inhibitor 2A)
Diseases named in the same sentence as CDKN2A in open-access papers (continued):
Sharing a sentence is not in itself a finding about the gene and the disease.
meningioma (continued). "As mentioned, loss of H3K27me3 modifications has been associated with meningioma recurrence in retrospective clinical studies, and hypermethylation of TIMP3, CDKN2A, and TP73 has been correlated with meningioma grade." (PMID 38001599, 2023). "The group of meningioma patients diagnosed with heterozygous CDKN2A/B deletions exhibited PFS rates of 70.2%, 55.9%, and 3.4% at 12, 24, and 60 months, respectively." (PMID 38017560, 2023). "Patients with meningiomas harboring homozygous CDKN2A/B deletions similarly have significantly worse outcomes and more rapid time to recurrence." (PMID 37010677, 2023). "Generally, the overall prevalence of any type (heterozygous or homozygous) of CDKN2A/B deletions in meningiomas was 4.9%." (PMID 38017560, 2023). "Homozygous focal deletions of the cyclin-dependent kinase inhibitor 2A (CDKN2A) gene have been observed in highly proliferative meningiomas, such as anaplastic WHO grade 3 meningiomas." (PMID 37370707, 2023). "The median time to meningioma progression in the CDKN2A/B wild-type arm was 180.0 (95% CI 145.7–214.3) months, whereas in those with a homo- or heterozygous CDKN2A/B deletion median PFS time was 14.8 (95% CI 10.0–19.6) months (p < 0.0001)." (PMID 38017560, 2023). "Across the four included investigations regarding meningioma patients with CDKN2A/B status and available PFS data, the pooled prevalence of CDKN2A/B deletion (hetero- or homozygous) was 0.049 (95% CI 0.040–0.057)." (PMID 38017560, 2023). "Homozygous deletion of CDKN2A/B was recently incorporated into the World Health Organization classification for grade 3 meningiomas." (PMID 37093270, 2023). "Relatively few gene-level alterations, including CDKN2A/B, TERT, and NDRG2 (N-myc downstream-regulated gene family member 2), have been strongly associated with the malignant progression of meningioma." (PMID 36836440, 2023). "Both meningioma patient groups with either hetero- or homozygous CDKN2A/B deletions had significantly shorter PFS times compared to those with CDKN2A/B wild-type." (PMID 38017560, 2023). "created an integrated scoring system by combining chromosomal losses, CDKN2A losses, and mitotic count to separate meningiomas into three separate groups." (PMID 36686824, 2022). "Other recently identified mutations are linked to a phosphatase tensin homolog on chromosome 10 (PTEN), as well as cyclin kinases CDKN2A/CDKN2B, main tumor suppressor genes predominantly implicated in meningioma progression." (PMID 36551712, 2022). "The last WHO classification (5th Edition, 2021) integrated a TERT promoter mutation or a homozygous deletion of CDKN2A and/or CDKN2B as new criteria for the recognition of grade 3 meningiomas." (PMID 36551712, 2022). "Recurrent genomic alterations, mainly involving CDKN2A/CDKN2B locus loss on 9p, are found frequently in meningiomas at recurrence as well as at progression and are associated with prognosis." (PMID 36230612, 2022). "To evaluate the clinicopathologic relevance regarding the molecular diagnostic criteria in WHO CNS 5, we assessed the TERT promoter and CDKN2A/B status of meningioma." (PMID 35774130, 2022). "In higher grade meningiomas, mutations of TERT promoter and deletion of CDKN2A/B seem to have a prognostic value." (PMID 34679551, 2021). "In a series of 30 cases of variable histotype and grade, the homozygous deletion of CDKN2A/B was identified in three anaplastic (grade III) meningiomas with ≥ 20 mitoses/10 HPF and that recurred." (PMID 33670055, 2021). "Data published recently have also shown that activating TERT promoter mutations, frequent inactivation of BAP1, deletions of CDKN2A/B, and mutations in DMD are frequent in meningiomas with malignant histological progression." (PMID 34778063, 2021). "More recently, mutations in TERT (telomerase reverse transcriptase) and CDKN2A (cyclin-dependent kinase inhibitor 2A) have been shown to be potential prognostic indicators in higher grade meningiomas." (PMID 34300316, 2021).
meningioma (continued). "Alterations on chromosome 9p21 during meningioma progression have been found to induce losses of the tumor suppressor genes CDKN2A (p16INK4a), p14ARF, and CDKN2B (p15INK4b)." (PMID 34359639, 2021). "In large-scale genomic studies of meningioma, higher grade (WHO grade II and III) meningioma were in some studies exclusively related to pathogenic variants in NF2, associated with mutations in the TERT promoter, and deletion of 1p and CDKN2A." (PMID 33262459, 2021). "Bi-allelic CDKN2A/B deletions occurred in 93/472 of all NF2-mutant (19.7%) versus 30/377 in NF2-wt meningiomas (8.0%) (p = 0.0001)." (PMID 33087175, 2020). "The deletion of the CDKN2A gene promoted the malignant progression of meningioma, indicating poor outcome." (PMID 33042832, 2020). "CDKN2A/B alterations were significantly enriched in WHO grade 3 meningiomas (n = 75/176, 42.6%) in comparison to WHO grade 2 (n = 47/441, 10.6%, p = 0.0001)." (PMID 33087175, 2020). "Our data demonstrates an independent adverse effect of CDKN2A/B homozygous deletion on the time to progression of patients with meningiomas." (PMID 32642869, 2020). "Here, we sought to determine the overall prognostic role of the CDKN2A/B status in a cohort of 528 meningioma patients with clinical follow-up data, covering all WHO grades and various subtypes." (PMID 32642869, 2020). "Other common driver mutations in our cohort such as CDKN2A, ARID1A, BRCA1, NF1, AKT1, SMO, PIK3CA have similarly been noted in various prior sequencing studies of meningiomas." (PMID 31191822, 2019). "In summary, this study provided evidence that p14ARF, RASSF1A, p15INK4B (CDKN2B), RUNX3, GATA6, p16INK4A (CDKN2A), NDRG2 and to lesser extent ATM and RARβ promoter methylation are associated with the development of meningiomas." (PMID 25648363, 2015). "Atypical and malignant meningiomas have more complex genetic alterations with losses of the G1-S phase cell cycle checkpoint regulators, CDKN2A and CDKN2B, and p14ARF on chromosome 9p contributing to more aggressive meningioma phenotypes." (PMID 17937814, 2007). "Losses of cyclin dependent kinase inhibitors, CDKN2A and CDKN2B, have been implicated as the tumor suppressor genes on chromosome 9p responsible for malignant meningioma phenotypes." (PMID 17937814, 2007). "NF2 mutation severity score, loss of chromosome 1p, deletion of CDKN2A/B, and global methylation status have been identified as negative prognostic factors for meningioma." (PMID 40562609, 2025). "In this study, we demonstrate that in meningiomas, CDKN2A copy number status may differ from the MTAP status." (PMID 40227557, 2025). "In meningiomas, elevated CDKN2A mRNA expression may serve as a biomarker of clinical aggressiveness, and deletion of pure-transgenic CDKN2A/B will result in a worse prognosis." (PMID 39253931, 2025). "Nevertheless, we propose that negative p16 immunostaining in higher-grade meningiomas suggests potential CDKN2A loss." (PMID 40227557, 2025). "Emerging data suggest that molecular and epigenetic features—including CDKN2A deletion, TERT promoter mutation, copy number analyses, and methylation-based classification—will be important to integrate into risk stratification frameworks for meningioma." (PMID 41497451, 2025). "In addition, Cyclin-dependent kinase inhibitor 2A/B (CDKN2A/B) homozygous deletion is one of the molecular alterations that support CNS WHO grade 3 designations for meningiomas." (PMID 39409918, 2024). "CDKN2A FISH analysis was performed on 43 meningiomas in a CLIA-certified CAP-accredited laboratory." (PMID 39409918, 2024). "The deletion of the CDKN2A/B gene, known to influence tumor progression and clinical outcomes, has been corroborated in other malignant central nervous system (CNS) neoplasms, including meningiomas." (PMID 39593128, 2024). "Focal MTAP expression meningiomas can be assessed with CDKN2A FISH to determine true CDKN2A status." (PMID 39409918, 2024).
meningioma (continued). "Similarly, a study of 183 atypical meningiomas identified CDKN2A/B HD in a mere 4% of WHO grade 2 meningiomas." (PMID 39202270, 2024). "Only 20/41 (48%) of meningiomas with intact CDKN2A status showed expression of p16." (PMID 39409918, 2024). "P16 appears to be a less reliable marker of CDKN2A status in meningiomas." (PMID 39409918, 2024). "Meningiomas not defined by NF2 mutations commonly have deletions in CDKN2A/B located on chromosome 9p, as well as TRAF7 mutations on chromosome 16p." (PMID 39796693, 2024). "Homozygous CDKN2A deletions occur in approximately 4.9% of meningiomas." (PMID 39409918, 2024). "MTAP IHC is a promising surrogate marker for the evaluation of CDKN2A status in meningiomas." (PMID 39409918, 2024). "Likewise, the rate of homozygous CDKN2A/B deletions was approximately 7% in grade 2 meningiomas in another cohort." (PMID 38720399, 2024). "For both institutions, the sensitivity of the absence of p16 immunostaining for identifying meningiomas with CDKN2A homozygous loss was 50% (1/2)." (PMID 39409918, 2024). "To confirm that CDKN2A mRNA expression could be predictive of outcome, we fit a univariable and multivariable Cox proportional hazards model on all meningiomas with available PFS data." (PMID 37093270, 2023). "In addition, CDKN2A/B alterations were found in only 13.1% of recurring tumors in an analysis of 583 meningiomas and in only 1 of 12 recurring atypical meningiomas (classified according to WHO 2016) by our group." (PMID 37296907, 2023). "This may explain the progressive, step-wise increase in CDKN2A expression we see in more proliferative meningiomas as we move up to higher WHO grades and increasingly more aggressive molecular/methylation groups." (PMID 37093270, 2023). "Pharmacological inhibition of cyclin-dependent kinases CDK4/6 could represent a particularly promising strategy in higher-grade meningiomas with high mitotic activity independently from CDKN2A/B status." (PMID 36181606, 2023). "The degree of associated 9p loss did not appear to significantly alter the outcomes of meningiomas with CDKN2A/B homodel or heterodel." (PMID 37093270, 2023). "Recent studies demonstrate that contrary to the expected effect of CDKN2A/B loss, elevated levels of CDKN2A mRNA are associated with lower PFS and more malignant molecular and methylation classes in CDKN2A/B intact/wild-type meningiomas." (PMID 38017560, 2023). "Therefore, we combined a large repository of recently published datasets along with newly generated molecular data in order to comprehensively characterize the spectrum of CDKN2A alterations in meningiomas." (PMID 37093270, 2023). "Interestingly meningiomas with CDKN2A/B deletions also appeared to have worse outcomes compared to CDKN2A/B intact/wt meningiomas in each molecular group (MG) except for in MG4, which are already comprised of the most biologically aggressive meningioma cases." (PMID 37093270, 2023). "This too, may explain the similarities in the upregulated transcriptomic pathways shared between meningiomas with CDKN2A deletion and CDKN2Ahigh cases." (PMID 37093270, 2023). "Thus, homozygous as well as heterozygous CDKN2A/B deletions seem to be strong biomarkers for PFS as a potential surrogate marker for overall survival in WHO grade 2 or 3 meningiomas." (PMID 38017560, 2023). "Interestingly, meningiomas with CDKN2A/B heterodel had a more heterogenous level of mRNA expression, despite having clinical outcomes as poor as those with homodel." (PMID 37093270, 2023). "Moreover, according to the fifth edition, any meningioma with TERT promoter mutation and/or CDKN2A/B homozygous deletion is considered grade 3." (PMID 37760490, 2023). "Also consistent with our mRNA data, CDKN2Ahigh meningiomas had the highest p16 protein levels while meningiomas with CDKN2A homodel had the lowest, with CDKN2Alow meningiomas as an intermediate between the two." (PMID 37093270, 2023).
meningioma (continued). "There may exist relatively small subcohorts of WHO grade 1 and 2 meningioma patients exhibiting heterozygous CDKN2A/B deletions, and these cases might be currently underestimated in terms of postoperative risk stratification for tumor progression." (PMID 38017560, 2023). "This suggests that Rb-deficiency may be more common in CDKN2Ahigh meningiomas, and those that are Rb-intact, may behave like meningiomas with CDKN2A deletions due to Rb hyperphosphorylation and allowance for cell cycle progression." (PMID 37093270, 2023). "Furthermore, a recent study confirmed the role of CDKN2A mRNA expression as a biomarker of clinically aggressive meningiomas, especially in Grade 3 meningiomas." (PMID 37686527, 2023). "However, even in cohorts enriched for high grade meningiomas, CDKN2A/B homodel is rare, reported in only 1.7–6.7% of patients." (PMID 37093270, 2023). "Irrespective of CDKN2A/B loss, the transcriptional level of CDKN2A/B harbor prognostic significance in meningioma." (PMID 38017560, 2023). "In samples with matched RNAseq data on the same tumors with DNA methylation, meningiomas with CDKN2A/B deletions had significantly lower CDKN2A mRNA expression compared to CDKN2A/B intact/wt meningiomas in the Toronto cohort, but not in the transcriptomic validation cohort." (PMID 37093270, 2023). "Furthermore, WHO grade 1 or 2 meningiomas with a heterozygous CDKN2A/B deletion were compared WHO grade 2 or 3 meningiomas with a CDKN2A/B wild-type status." (PMID 38017560, 2023). "However, all homozygous tumors would be classified as malignant in accordance with the newly implemented WHO classification 2021 due to CDKN2A/B homozygous deletion as an independent criterion of WHO grade 3 meningiomas." (PMID 37898750, 2023). "Overall CDKN2A/B deletion was rare, present in only 108 of 1506 patients (7.1%, excluding the IHC cohort), even though several of the cohorts we included were enriched for clinically aggressive meningiomas with early recurrences." (PMID 37093270, 2023). "However, even the heterozygous CDKN2A/B showed a significantly shortened time to meningioma progression (log-rank test: p < 0.0001) compared with the CDKN2A/B Wild-type arm." (PMID 38017560, 2023). "The mutation or deletion of CDKN2A and CDKN2B has been linked to a poorer prognosis in meningioma." (PMID 35712491, 2022). "However, gaining of additional molecular features of high-grade meningioma, such as 22q/NF2 loss, chromosome instability, and homozygous CDKN2A/B deletions leads to tumor progression." (PMID 35440040, 2022). "Furthermore, 8% harbored mutations in TERT, CDKN2A/B, or BAP1 of which 6% occurred in grade 1 meningiomas." (PMID 35299730, 2022). "The CNV profiles showed a homozygous loss of CDKN2A/B, loss of PTEN, and/or NF2 genes in 0%, 0%, and 50% of grade 1 meningiomas; 0%, 42%, and 91% of grade 2 meningiomas; and 40%,100%, and 100% of grade 3 meningiomas, respectively." (PMID 36551712, 2022). "One meningioma that featured only minor atypical criteria had the homozygous deletion of CDKN2A/B, in the absence of NF2 mutation." (PMID 33670055, 2021). "Moreover, deletions of CDKN2A/CDKN2B are of poor prognostic factors in anaplastic grade III meningiomas." (PMID 34359639, 2021). "Two recurring meningiomas had the inactivation of cell cycle inhibitors; one (13M) had a CHEK2 truncating mutation, coupled with the deletion of the second allele, the other (21M) had CDKN2A/B homozygous deletion." (PMID 33670055, 2021).
meningioma (continued). "Only one WHO grade 1 meningioma had a CDKN2A/B alteration (n = 1/220, 0.4%, p = 0.0001)." (PMID 33087175, 2020). "Interestingly, meningiomas harboring CDKN2A/B alterations were significantly more common in males (n = 77/123, 62.6%) than in females (p = 0.0001)." (PMID 33087175, 2020). "This may suggest CDKN2A/B deletion as independent criterion for identification of highly aggressive (i.e. WHO grade III) meningiomas." (PMID 32642869, 2020). "In conclusion, our study demonstrates that homozygous deletion of CDKN2A/B is highly prognostic in meningiomas and may be a useful, independent molecular biomarker for grading of these tumors." (PMID 32642869, 2020). "In addition to the CDKN2A/CDKN2B genes, the KLF4 (Kruppel like factor 4) gene has also been recently reported to be mutated in meningiomas (particularly among secretory tumors) in association with lack of NF2 mutation." (PMID 25965831, 2015). "Additionally, inactivation through hypermethylation of CpG islands has also been reported in a smaller proportion of meningiomas, including hypermethylation of CDKN2A/p16INKa in 8-17% of cases, CDKN2A/p14ARF in 4-13%, and CDKN2B/p15ARF in 4% of these tumors." (PMID 25965831, 2015). "Interestingly, they also found a cohort of meningiomas with a high CDKN2A mRNA expression (CDKN2Ahigh), which exhibited similarly aggressive outcomes to those with homozygous CDKN2A deletion and was enriched with transcriptomic pathways similar to those found in the CDKN2A homozygous loss group." (PMID 40227557, 2025). "Recently, there have been studies conducted with mesothelioma, various epithelial tumors, meningioma, and pleomorphic xanthoastrocytoma (PXA) in order to use methylthioadenosine phosphorylase (MTAP) immunohistochemical expression loss as a surrogate biomarker to detect CDKN2A HD status." (PMID 38109891, 2024). "The Kalamarides lab has previously developed several meningioma GEMMs relying on the Adenovirus Cre (AdCre)-mediated deletion of the Nf2 gene in PGDS (Prostaglandin D synthase)-expressing arachnoid cap cells in mice either in a wild-type or Cdkn2a null background." (PMID 38571886, 2024). "In addition, CDKN2A/B status is considered an independent prognostic factor in meningioma." (PMID 38758750, 2024). "Meningiomas are considered grade 3 when they have 20 or more mitoses in 10 HPF of 0.16 mm2, and/or frank histological anaplasia with a morphology resembling a carcinoma, melanoma, or sarcoma, and/or TERT promoter (pTERT) mutation, and/or CDKN2A/B homozygous deletion (HoDe)." (PMID 37296907, 2023). "Importantly, CDKN2Alow meningiomas actually appeared to have an intermediate level of CDKN2A mRNA expression, higher than the “null” level of expression seen in CDKN2A homodel cases but lower than the highest levels of expression observed in the CDKN2Ahigh cases." (PMID 37093270, 2023). "Furthermore, nearly one third of all WHO grade 3 meningiomas have CDKN2A/B deletions, which necessitates further research on markers identifying patients who might benefit from CDK4/6 inhibitors." (PMID 38017560, 2023). "Notably, nearly one third of the WHO grade 3 meningiomas have a homozygous CDKN2A/B deletion." (PMID 38017560, 2023). "Indeed, in a heterogeneous cohort of 659 meningiomas, including primary and recurrent tumors, of all three CNS WHO grades, and with either total or subtotal surgical resection, CDKN2A/B HeDe was found in 15 cases in association with shorter progression-free survival." (PMID 37014425, 2023). "However, the majority of HM meningiomas did not have any copy number loss of CDKN2A/B or aberrant activation of the FOXM1 pathway." (PMID 36840836, 2023). "We now recognize that patients with meningiomas harboring CDKN2A homozygous deletion or TERT promoter mutation regardless of histologic grade have poor clinical outcomes similar to patients with histologically diagnosed anaplastic (CNS WHO grade 3) meningiomas." (PMID 36723772, 2023).